IL10 (interleukin 10)
Diseases named in the same sentence as IL10 in open-access papers (continued):
Sharing a sentence is not in itself a finding about the gene and the disease.
tumor (continued). "These immune suppression networks include the immunosuppressive cells such as tumour-associated macrophages (TAM), MDSCs, and regulatory T cells, and the immunosuppressive cytokines, TGF-β and interleukin-10 (IL-10)." (PMID 28137309, 2017). "Studies showed that when macrophages are exposed to a tumor microenvironment that overexpresses IL-4 and IL-10, the macrophages are polarized and differentiate into M2 macrophages, which are also known as tumor associated macrophages (TAMs)." (PMID 28592924, 2017). "NK cells are a central component of the innate immune system, secreting different cytokines like IFNγ, interleukin-10 or TNFα to stimulate other immune cells, and are capable to directly destroy tumor cells." (PMID 28690853, 2017). "IL-10, whose expression is thought to be correlated with tumor promotion, was also significantly increased." (PMID 28301579, 2017). "Conversely, M2 macrophages express the scavenger receptor, the mannose receptor and IL-10, which facilitate tumour progression amongst other things." (PMID 28166767, 2017). "The deletion of IKKβ restored TAM responsiveness which was manifested in tumor growth inhibition, low IL-10, low ArgI, and high IL-12 production." (PMID 28197019, 2017). "Tumor-derived HMGB1 inhibited the cytotoxic anti-tumor CD8+ cells by potentiating regulatory IL-10-producing T cells." (PMID 28404891, 2017). "Radix Glycyrrhizae polysaccharide (GP) was demonstrated to decrease the mRNA expression of Foxp3 and IL-10 and upregulate Th1/Th2 cytokine ratio in serum in tumor bearing mice, which putatively inhibited tumor growth." (PMID 28804502, 2017). "The impairment of metastatic potential of the B16F10 cells was correlated with low activation of the ERK signaling pathway, supporting the idea that the production of IL-10 by B-1 cells influences the behavior of the tumor." (PMID 29145406, 2017). "Tumors, in turn, inhibit this anti-tumor activity by producing immunosuppressive cytokines, such as IL-10 and TNF-β, and inducing immunosuppressive cells, such as Tregs, tumor-associated macrophages (TAMs), and myeloid-derived suppressor cells (MDSC)." (PMID 28406993, 2017). "SBE treatment significantly down-regulated Th17 and Treg related cytokine, IL-17, TGF-β, IL-10 in the serum of tumor bearing mice (P < 0.01)." (PMID 28086772, 2017). "Tregs depress the antitumor immune response, depending on the secretion of TGF-β and IL-10, whereas the role of IL-17 in tumor immunity remains fully undefined." (PMID 29383114, 2017). "Tumor-induced or IL-10-induced inhibition of DC functional maturation can be abrogated by blocking of STAT3 signaling." (PMID 28346397, 2017). "The expression of immunoinhibitory molecules and cytokines, for example, IL-1β, VEGF, IL-10, and TGFβ and downregulation of immunostimulatory cytokines (e.g., IL-2, IL-12, IL-15) allow tumor to escape from immune control." (PMID 28052005, 2017). "Many suppressive pathways, including the COX2, IL-10, NOS2 and IDO1 mechanisms described here, have been implicated in tumor-associated immune dysfunction within the human TME." (PMID 29163789, 2017). "Tumor cells produce cytokines responsible for the recruitment and polarization of macrophages to M2 profile such as IL-4, IL-10, IL-13, and TGF-β, as well as chemokines such as CCL2 (MCP-1), CCL3, and CCL14." (PMID 28970834, 2017). "The results of this study suggest that high expression of IL-10 by NKp30c-expressing NK cells induces B7-H6 expression on tumor, thereby potentiating further expression of this immunosuppressive cytokine." (PMID 28424697, 2017). "We also noted remarkably elevated iNOS and NO production and decreased tumor growth-associated cytokines such as IL-10, TGF-β, IL-6, and VEGF in tumor tissues of recipient animals." (PMID 28243242, 2017). "IL-10 is a well known immunosuppressive cytokine in tumor microenvironment, and its increased levels are correlated with poorer prognosis of cancer patients." (PMID 29029545, 2017).
tumor (continued). "IL-10 is an anti-inflammatory cytokine with pleiotropic functions, able to exert both antitumor and tumor-promoting effects." (PMID 29163540, 2017). "The tumor microenvironment is a complex system, including various kinds of cells, e.g., tumor cells, immune cells, etc., and cytokines, e.g., IL-6, IL-10, TGF-β, etc.." (PMID 28234961, 2017). "Anti-IL-10 in addition with an inflammatory agent like CpG results in the transition of TAMs from M2 to M1 phenotype, resulted in tumor inhibitions." (PMID 28694739, 2017). "It has been shown that the immature phenotype of DCs is mediated by tumor-induced expression of IL-10 and TGF-β." (PMID 28536351, 2017). "Immune suppressive cytokines, TGF-β1 and IL-10, are representative factors forming a tumor-favorable environment." (PMID 28282460, 2017). "In contrast, alternatively activated GAMs (M2 macrophages) exert immunosuppressive and tumor promoting characteristics through secretion of immunosuppressive cytokines such as IL-10 and TGF-β." (PMID 28346397, 2017). "It is suggested that IL-10 can suppress the tumor development through the activation of natural killer, CD8+ and CD4+ T lymphocytes." (PMID 28846716, 2017). "Based on these observations, we guessed that less IL-10 was beneficial for immunological monitoring, reducing the possibility of tumor cell survival." (PMID 29029504, 2017). "A pegylated formulation of IL-10 is currently undergoing clinical evaluation and has demonstrated potent anti-tumour activity in patients with metastatic renal cell carcinoma." (PMID 29157300, 2017). "Despite their less mature phenotype, IL-10+ DC displayed higher levels of PD-L1, a molecule associated with TLR-activated DC which is involved in tumor immunosuppression." (PMID 27926522, 2017). "Of the two major macrophage phenotypes (M1 and M2), the M2 phenotype of TAMs in the tumor region are basically regulated by a subset of tumor-secreted factors, such as M-CSF, IL-4, IL-13 and IL-10." (PMID 28032600, 2017). "Conversely, the anti-inflammatory cytokines IL4 and IL10 were found at significantly lower concentration in the spleen of only the orthotopic tumor-bearing group when compared to sham." (PMID 27901481, 2017). "As a potential cancer therapy, IL-12p70 reversed the immunosuppressive phenotype of tumor-associated macrophages in a subcutaneous murine model, with concomitant reduced synthesis of CCL2 and IL-10." (PMID 28966800, 2017). "The levels of related cytokines (IL-6, IL-10 and IL-12) were also detected by ELISA using the homogenate of tumor tissues." (PMID 29383114, 2017). "In mice, 4-1BB stimulation leads to enhanced NK cell effector mechanisms, but in humans 4-1BB signaling inhibits NK effector activity and reverse signaling through 4-1BBL on tumor cells can induce IL-10 and TNF-α." (PMID 28515726, 2017). "In particular, TFG-β, IL-10, and regulatory T cell populations are prevalent components of the tumor microenvironment known to suppress anti-tumor immunity." (PMID 29167448, 2017). "Among the soluble factors contributing to TAM polarization, tumor progression and a poor clinical outcome, interleukin 10 (IL-10), IL-6, transforming growth factor β (TGFβ) and arachidonic acid play a prominent role." (PMID 28327095, 2017). "On the contrary when mTOR was active, knocking-down the intrinsic mTOR inhibitor TSC2, TAMs produced more IL-10 and both tumor growth and angiogenesis increased." (PMID 28197019, 2017). "Here we characterized IL-10-producing cells in different tumor models treated with therapeutic vaccines." (PMID 27926522, 2017). "Consistently, upon adoptive transfer, MDSCs induced by RAE1ε significantly promote CT26 tumour growth in IL‐10‐ and arginase‐dependent manners." (PMID 28276625, 2017). "IL-6 and IL-10 belong to T-helper type 2 cell cytokines, contributing to inhibition of host's immune system and induction of tumor progression." (PMID 29109622, 2017).
tumor (continued). "These cells expressed IL-10 and PD-L1, and mediated resistance to immunogenic chemotherapy by suppressing anti-tumor CTL." (PMID 28134800, 2017). "The immunosuppressive and anti-inflammatory cytokine IL-10, inhibits tumour development, tumour progression, modulates apoptosis and suppresses angiogenesis during tumour regression." (PMID 28764778, 2017). "IL-10 from MDSCs has been suggested as a major determinant of immunogenic activity in tumor microenvironments." (PMID 27965469, 2017). "In tumor tissues, CSF-1 or IL-10 produced in tumor cells induce the differentiation of TAMs to M2 macrophages." (PMID 29286292, 2017). "In parallel, TLR7/8 stimulation also induced regulatory genes, such as IL-10, and anti-tumor factors, such as high-mobility group box 1 protein (HMGB1)." (PMID 29190907, 2017). "IL-10 is a highly pleiotropic cytokine that has been characterized as both a tumor promoter and an inhibitor of tumor progression depending on context." (PMID 29137411, 2017). "PD-L1 tumor abundance was negatively correlated with the serum cytokine IL10 and positively correlated with CCL22." (PMID 28266500, 2017). "Tumor immune evasion is mediated, at least in part, by a network of soluble immunomodulatory factors, such as IL-6 and IL-10, as well as transforming growth factor β (TGF-β), which are secreted by tumor, stroma, and inflammatory cells." (PMID 28536351, 2017). "For instance, tumor and T-regulatory cell-derived IL-10 can skew macrophages toward an anti-inflammatory phenotype characterized by activation of STAT3 and increased expression of CD163, CCL18, and SOCS3." (PMID 28881599, 2017). "Tumor IL-10 levels were also elevated more significantly after treatment with Ad-TD-IL12 compared to Ad-TD-nsIL12 or Ad-TD-LUC." (PMID 29123084, 2017). "The immunosuppressive activity of not only IL-10 and PGE2 but also other OC-associated factors on such accessory cell types will negatively influence the induction and the effectiveness of anti-tumour immunity." (PMID 28410380, 2017). "In turn, this CD45RA−CCR7− Treg subset suppresses CD8+ T-cell anti-tumor function via IL-10 secretion and cell–cell contact mechanisms, and, in doing so, contribute to the immunosuppression and GC progression." (PMID 28817117, 2017). "Tumor-promoting macrophages express higher IL-10 levels, while tumor-reactive macrophages produce predominantly IL-12." (PMID 29105655, 2017). "In fact, PF in OC patients creates a complex and highly pro-tumor microenvironment with elevated levels of IL-6, IL-8, IL-10, IL-15, IP-10, MCP-1, MIP-1β, and VEGF." (PMID 28589429, 2017). "Local irradiation in combination with CD8+ T cell transfer induced an enhanced expression of IL-12p40 and IFNγ (M1 markers) and a reduced expression of IL-10 (M2 marker) in tumor tissue lysate." (PMID 28769933, 2017). "M2b cells are induced by immune complexes, lipopolysaccharides, IL-1R and TLRs ligands; they produce cytokines such as IL-1, IL-6, TNF-α, and IL-10, acting in the metastasis control, suppressing tumor growth and inducing a Th1 response." (PMID 28970834, 2017). "TAMs produce high levels of immunosuppressive IL-10 and stimulate angiogenesis that further supports tumor growth." (PMID 28348554, 2017). "In fact, when IL-10 is elevated in blood during advanced GC, it leads to the inability to eliminate tumor cells." (PMID 28558708, 2017). "Mechanistically, our and other labs noticed that IL-10- or IL-4-stimulated macrophages export iron to accelerate tumor growth by supplying iron to actively proliferating tumor cells." (PMID 28979267, 2017). "BM cell-induced secretion of IL-10 from MCs can attribute tumor-specific immune surveillance in the tumor microenvironment and modulate cell growth and extracellular matrix (ECM) remodeling." (PMID 28626727, 2017). "Local signals in the tumor microenvironment (IL-4, IL-6, IL-10, PGE2, CSF-1, and transforming growth factor-β, TGF-β) polarize macrophages into alternative, protumoral M2-like cells." (PMID 28197019, 2017).
tumor (continued). "Developed Bregs can suppress the synthesis of IFN-γ by CD8+ T cells in IL-10-dependent mechanism, which results in the inhibition of anti-tumor immunity." (PMID 28477096, 2017). "This study also reported an increase in IFN-γ and granzyme B expression and a three-fold increase in tumor-infiltrating cytotoxic leukocytes in mice receiving IL-10." (PMID 29137411, 2017). "Another feasibile strategy to modulate tumor microenvironment signalling is to directly inhibit TGFβ, IL-10, and/or IL-4 signaling." (PMID 28331617, 2017). "Among the soluble factors contributing to TAM polarization, tumor progression, and a poor clinical outcome, IL-6, IL-10, TGFβ, and AA play a prominent role." (PMID 28275576, 2017). "MSCs profoundly reduced infiltration of macrophages, TNF-α-producing dendritic cells (DCs), TNF-α-, and IL-17-producing CD4+ T cells but increased IL-10-producing CD4+ T lymphocytes in the lungs of tumor-bearing animals." (PMID 28798777, 2017). "At the site of the tumor, the high production of IL-10 derived from TAMs indirectly inhibits T cell activation by down regulating IL-12 production by dendritic cells, which, in turn, prevents the TCD8+ response." (PMID 28970834, 2017). "In the tumor microenvironment, neutrophils secrete a variety of cytokines including interleukin-2, interleukin-10, and tumor necrosis factor α, which further promote cancer development." (PMID 28441396, 2017). "The results of our study showed SBE treatment up-regulated Th1 cytokine (IL-2 and IL-12p70) and down-regulated Th17 (IL-17) and Treg (TGF-β and IL-10) related cytokine in the serum of tumor bearing mice." (PMID 28086772, 2017). "TAM-derived IL-10 suppresses the expression of IL-12, which is considered as a potential anti-tumour cytokine." (PMID 29065107, 2017). "For example, when monocyte-derived M2 Mφs were differentiated in the presence of ZA, they had reduced expression of CD206 and IL-10, and an impaired capacity to promote angiogenesis and tumour cell invasion." (PMID 28501938, 2017). "In this study, in HCT-116 and HT-29 cells, we found that GAS5 significantly inhibit the release of IL-10 and VEGF-A, which indicates that GAS5 is involved in the tumour-associated inflammatory response." (PMID 28099146, 2017). "On the other hand, HMGB1 increases MDSC (myeloid-derived suppressor cells)—macrophage crosstalk and production of IL-10, thereby skewing macrophages toward a type II tumor—promoting phenotype." (PMID 28196513, 2017). "Previous studies on the roles of IL-10 in tumor immunosuppression mainly focus on its biochemical effects." (PMID 28234961, 2017). "On the other hand, removal of IL-10 inducing T cell epitopes from the insulin-like growth factor-binding protein 2 (IGFBP2) vaccine conferred potent anti-tumor activity." (PMID 28211521, 2017). "Tumor-infiltrating T cells such as Th2 cells, immune complexes, or stromal element-derived cytokines like IL-10, and TGF-β can drive TAMs into an M2-like phenotype." (PMID 28620389, 2017). "The frequencies of tumor-associated immunosuppressive factors, including the COX2, IL-10, NOS2 and IDO1 mRNA was abrogated by the addition of COX2 inhibitor during the generation of CM from cancer ascites cells." (PMID 29163789, 2017). "Neoplastic cells and tumor-associated macrophages (TAM) secrete IL-6, CSF-1, IL-10, TGF-β, TNF-α, IL-1α, angiogenic and lymphangiogenic growth factors that promote tumor development." (PMID 28830415, 2017). "Regarding the immunological mechanisms underlying the observed enhancement of the tumor-specific immune response, we evaluated the effects of tumor antigen-loaded DCs plus lenalidomide combination therapy on inhibitory cytokine IL-10 production." (PMID 28460478, 2017). "IL-10 can be secreted by different types of cells, including tumour cells, and hematopoietic cells that infiltrate the tumour tissues." (PMID 28810829, 2017). "The recent studies on the roles of IL-10 in tumor immunosuppression mainly focus on its biochemical effects." (PMID 28234961, 2017).
tumor (continued). "We also tested if IL-10, an immunosuppressive cytokine often found within the tumor microenvironment, can repolarize macrophages into M(IL-10 + TGFβ)-like macrophages." (PMID 29084248, 2017). "Tumor derived molecules, such as IL-4, IL-10, and transforming growth factor-β1 (TGF-β1), have been proposed as major factors inducing M2-polariziation of TAMs." (PMID 28032600, 2017). "Here we have analyzed the role of IL-10, a cytokine with controversial effects on tumor immunity, reported as detrimental for T-cell priming during therapeutic vaccination." (PMID 27926522, 2017). "Interleukin-10 (IL-10) induces an immunosuppressive microenvironment including M2 macrophages, inhibiting anti-tumor immunity." (PMID 29100307, 2017). "The M2 shift observed in a subset of TAMs was characterized by high IL-10 expression leading to immunosuppression and subsequent tumor promotion." (PMID 28966800, 2017). "By producing immunosuppressive cytokines such as TGF-β and IL-10, the tumor can favor Treg proliferation and survival over anti-tumor T cell subsets within the tumor microenvironment." (PMID 29037250, 2017). "IL-10 has a relevant effect on the tumour microenvironment, as it is present on TAMs and CD8+ T cells." (PMID 29089667, 2017). "In this context, diverse pathways for IL-10 production by TAMs have been described, highlighting their contribution to an immunosuppressive state in the tumour stroma." (PMID 28381274, 2017). "TAMs acquire, possibly by cancer-derived factors like IL-10, the capacity to produce high levels of Gas-6 that promotes tumour development." (PMID 28381274, 2017). "Since IL-10 plays an inhibitory role even during vaccination of naive tumor-free mice, we started identifying IL-10+ cells in this setting." (PMID 27926522, 2017). "IL-10 is a multifunctional negative regulatory factor and promotes tumor evasion of the immune response by downregulating the production of interferon-γ." (PMID 28881764, 2017). "In our model, as the age-induced IL-10 increase was reversed only in multiparous mice exposed to tumorigenic cells, we suggest that parity counteracts tumor immunosuppression by partially repressing M2 polarization of TAMs." (PMID 28966800, 2017). "After treatment period, cytokines, Interleukin 2, IL-6, IL-7, IL-10, IL-15, 1 L-17 and TNFα in CT-26 tumor bearing BALB/c mice serum were analysed." (PMID 29246138, 2017). "MDSCs are critical in suppressing the adaptive and innate immune system during tumor progression by secreting immunosuppressive factors such as arginase and IL-10, so to observe this consistent finding in our tumor-expressed B7x model was interesting." (PMID 29137299, 2017). "Following stimulation with VEGF, IL-10, or prostaglandin E2, tumor endothelial cells express Fas ligand (FasL), which kills activated CD8+ T lymphocytes but not regulatory T cells." (PMID 28665313, 2017). "Tumour-resident DCs exhibited pronounced upregulation of Mapkapk2 by 1.9-fold as compared to splenic DCs and also expressed high levels of Il10, Tgfb1 and Arg1, suggesting robust immunosuppressive activity of these cells within the TME." (PMID 28924177, 2017). "To explore the in vivo relevance of above findings, we analyzed the correlation of IL-33 expression with Ki-67 proliferation index (PI), and expressions of arginase 1, IL-10 and FoxP3 in tumor tissues of NSCLC patients." (PMID 28978138, 2017). "The inhibition of STAT3 phosphorylation by oleanolic and corosolic acids, two naturally occurring triterpenes, suppressed tumor-mediated M2 polarization and IL-10 production by macrophages." (PMID 28197019, 2017). "Ultimately, Reg3g fosters a tumor environment consisting of Th2 cytokines IL-10 and TGF-β and of Tregs and MDSCs, accelerating tumor growth." (PMID 28880262, 2017).